C5AR2 (complement C5a receptor 2)
Diseases named in the same sentence as C5AR2 in open-access papers (continued):
Sharing a sentence is not in itself a finding about the gene and the disease.
epidermolysis bullosa acquisita (3 papers, 2022 to 2023). "In line with these latter findings, we recently reported a net pro-inflammatory contribution of C5aR2 to the pathogenesis of epidermolysis bullosa acquisita (EBA; 35)." (PMID 37275893, 2023). "While C5aR1 has been shown to exert a strong pro-inflammatory effect in these mouse models, both pro- and anti-inflammatory effects of C5aR2 have been reported in mouse models of BP and BP-like epidermolysis bullosa acquisita." (PMID 36466856, 2022).
atherosclerosis (2 papers, 2017 to 2024). A disease characterized by the build-up of fatty material and calcium deposition in the arterial wall resulting in partial or complete occlusion of the arterial lumen. "Also in atherosclerosis, the role of C5aR2 is less clear, in contrast to the clear-cut pathogenic role of C5aR1." (PMID 28706957, 2017). "Liu and colleagues investigated glycol- and lipometabolism in mice with different backgrounds fed with slightly distinct diet formula (high fat and high sugar compared to high fat) and found the protective role of C5aR2 in the development of atherosclerosis." (PMID 28706957, 2017). "This proatherogenic role of C5aR2 and its collaboration with C5aR1 were confirmed in vivo mouse models of wire-induced endothelial injury and high-fat diet-induced atherosclerosis." (PMID 28706957, 2017). "Contrarily, high C5aR2 expression in human atherosclerotic plaques reflected the advanced stages of atherosclerosis and correlated with excessive proinflammatory cytokine (TNFα and IL-1β) expression in human plaques." (PMID 28706957, 2017). "Here, C5aR2 levels were elevated in aortas of wire-injured mice or mice on high-fat diet (12 weeks), both of atherosclerosis-prone ApoE KO." (PMID 28706957, 2017).
Autoimmunity (2 papers, 2022 to 2025). The occurrence of an immune reaction against the organism's own cells or tissues. "The anaphylatoxins C3a and C5a are potent mediators and regulators of inflammation during the effector phase of autoimmunity through engagement of specific anaphylatoxin receptors, i.e., C3aR, C5aR1, and C5aR2 either on or in immune cells." (PMID 35958588, 2022). "These anaphylatoxins play important roles in the pathogenesis of allergy, autoimmunity, neurodegenerative diseases, cancer and infections through ligation of their receptors, i.e., the C3a receptor (C3aR), C5a receptor 1 (C5aR1), and the C5a receptor-like C5L2 (C5aR2)." (PMID 41373839, 2025).
bone fracture (2 papers, 2017 to 2021). "However, in C5aR2−/− mice, the concentrations of IL-1β, tumour necrosis factor (TNF) α and monocyte chemoattractant protein-1 (MCP-1) were significantly elevated after isolated fracture, indicating a pulmonary inflammatory response after bone fracture even in the absence of thoracic trauma." (PMID 29070810, 2017).
bullous pemphigoid (2 papers, 2018 to 2022). Bullous pemphigoid (BP) is the most common form of autoimmune bullous dermatosis. "While C5aR1 showed a proinflammatory effect in a mouse model of bullous pemphigoid and epidermolysis bullosa acquisita, C5aR2 demonstrated an anti-inflammatory effect in the same mouse model of bullous pemphigoid." (PMID 30524436, 2018).
cerebral malaria (2 papers, 2017 to 2024). A sequestration of Plasmodium falciparum in the brain, which can cause coma and/or seizures. "Both C5aR1 and C5aR2 (C5L2) receptors are involved in the physio-pathological functions of various ocular diseases, such as retinitis pigmentosa (C5L2), human and experimental cerebral malaria (only C5aR1), or choroidal neovascularization (in mice)." (PMID 39195219, 2024).
abscess (1 paper, 2015). An inflammatory process characterized by the accumulation of pus within a newly formed tissue cavity which is the result of a bacterial, fungal, or parasitic infection or the presence of a foreign body. "The larger abscesses in the kidneys of C5aR1−/− and C5aR2−/− mice induced higher levels of tissue destruction than the small emerging abscesses of wild type mice." (PMID 26512700, 2015). "More interesting was the observation that genetic deletion of either C5aR1 or C5aR2 resulted in enhanced production of neutrophil chemoattractant CXCL1 and in the infiltration of neutrophils into the infected kidneys, accelerated abscess formation and increased tissue damage." (PMID 26512700, 2015).
acute pyelonephritis (1 paper, 2024). "Similarly, we have also proved the pro-inflammatory and pathogenic role of C5aR1 and C5aR2 in acute pyelonephritis in mice." (PMID 39021433, 2024).
adenoma (1 paper, 2020). A neoplasm arising from the epithelium. "H&E staining showed that adenoma formation was accompanied by diffuse immune cells infiltration in the colons of WT, C3-deficient, and C5ar2-deficient mice, while more mucosa-associated lymphoid tissues suspected as tumors were observed in C5- and C5ar1-deficient mouse colons." (PMID 32754267, 2020).
ANCA-associated vasculitis (1 paper, 2020). "Blockade of C5aR1 prevented disease expression, and C5aR2 deficiency aggravated the disease condition; antagonism is being tested as a therapy for patients with ANCA-associated vasculitis." (PMID 32228220, 2020).
cognitive decline (1 paper, 2024). "Our proposed model delineates how cognitive decline associated with aging and neurodegenerative diseases arises from the coordinated activation of specific immune receptors—PIRB/LILRB2 and C5aR2 in neurons, TLRs and CR3 in astrocytes, and TLRs and CR3 in microglia." (PMID 38299364, 2024).
complement deficiency (1 paper, 2024). A genetic deficiency of any of the component of the complement system (including the classical, alternative, and terminal pathway components), that can either be acquired or inherited. "While broad complement deficiency did not drastically affect lung larvae burden, our study evidenced a drastic reduction of viable parasites count in BALF in C5aR1-/- mice, but not in C5aR2-/- or in C5aR1/2-/- double knockout mice." (PMID 39628481, 2024).
COVID-19 (1 paper, 2024). A disease caused by infection with severe acute respiratory syndrome coronavirus 2. "C3, C4 and C5 knockout mice together with Crry, DAF, C3aR and/or C5aR1 and C5aR2 knockout can be used for defining the role of complement in general and C3a-C3aR and C5a-C5aR signaling in the pathogenesis of severe COVID-19 and long COVID-19." (PMID 38368584, 2024).
diabetic nephropathy (1 paper, 2023). "In diabetic nephropathy, we identified positive correlations specifically with complement components C2 and C5 and receptors C5AR2 and CR2." (PMID 38069385, 2023).
glioma (1 paper, 2022). A benign or malignant brain and spinal cord tumor that arises from glial cells (astrocytes, oligodendrocytes, ependymal cells). "Overexpression of PCDH18, PPL, DEPP1, VASN, KCNE4, MYBPH, and C5AR2 in glioma and low expression of MARCH4 were associated with poor survival." (PMID 39281062, 2022). "Overexpression of PCDH18, PPL, DEPP1, VASN, KCNE4, MYBPH, and C5AR2 genes or low expression of MARCH4 gene in glioma patients was associated with poor survival." (PMID 39281062, 2022). "Through TCGA database, we identified that the eight key genes (PCDH18, PPL, DEPP1, VASN, KCNE4, MYBPH, C5AR2, and MARCH4) were associated with the survival of patients with glioma." (PMID 39281062, 2022).
Hypertension (1 paper, 2025). The presence of chronic increased pressure in the systemic arterial system. "Nevertheless, despite local complement playing a role in arteriosclerosis, knockout of C3aR1, C5aR1, and C5aR2 in a hypertension mouse model had no apparent effect on hypertension and cardiac injury." (PMID 40519170, 2025).
ischemic stroke (1 paper, 2019). A stroke disorder caused by obstruction of blood flow to the brain, due to thrombotic (local blood clot formation) or embolic (due to a blood clot or other material traveling from another site) event. "Although great progress has been achieved in the study of C5aR2 functions in vitro and in a variety of experimental animal models, little is known about its role in the CNS, including ischemic stroke." (PMID 31011487, 2019).
pancreatic ductal adenocarcinoma (1 paper, 2025). An infiltrating adenocarcinoma that arises from the epithelial cells of the pancreas. "We investigated the functions of complement 5a (C5a) and its receptors, C5aR1 and C5aR2, in forming the C5a-C5aR1 and C5a-C5aR2 signaling axes in the immune TME of pancreatic ductal adenocarcinoma (PDAC)." (PMID 41044172, 2025).
peritonitis (1 paper, 2024). Inflammation of the peritoneum (tissue that lines the abdominal wall and covers most of the organs in the abdomen). "Thus, in the inflammatory state of peritonitis, C5aR1 and C5aR2 signals might cooperate in modulating macrophage inflammatory responses." (PMID 39021433, 2024).
Pulmonary hemorrhage (1 paper, 2024). Pulmonary hemorrhage is a bleeding within the lungs. "On the other hand, the disruption of C5aR2 signaling alone or in combination with C5aR1 did not significantly alter pulmonary hemorrhage." (PMID 39628481, 2024).
renal fibrosis (1 paper, 2024). A final common manifestation of a wide variety of chronic kidney diseases characterized by glomerulosclerosis and tubulointerstitial fibrosis. "The C5aR2 knockout out mice also had enhanced TEC proliferation with reduced long-term renal fibrosis." (PMID 38892418, 2024).
tumor (56 papers, 2019 to 2026). "Conversely, mice deficient in C5aR1 or C5aR2 had higher tumor incidence, suggesting a tumor limiting role of these receptors in this particular model." (PMID 35860237, 2022). "In another AOM/DSS-induced CRC tumorigenesis, C5AR2 deficiency increased tumor progression, indicating that C5AR2 has an anti-inflammatory effect." (PMID 34595119, 2021). "The expression of C5AR2 and its correlations with prognosis, immune infiltration, tumor mutation burden (TMB), and microsatellite instability (MSI) in more than thirty types of cancers were described through GTEx, TCGA, PrognoScan, TIMER2.0, CCLE, HPA, and TISIDB database." (PMID 34595119, 2021). "Mechanistically, persistent NF-κB activation via C5aR2 in CAFs provides a survival niche for cancer stem cells, promoting tumour formation and chemoresistance." (PMID 39765018, 2025). "Targeting these C5aR2-expressing CAFs with a neutralising anti-C5aR2 antibody prevented tumour formation and improved tumour chemosensitivity against docetaxel or cisplatin." (PMID 39765018, 2025). "PCDH1+ tumor cells harbored the RHOB, C5AR2, HAPLN3, SERPINE2, ELN, EPS8L2, and ITGA5 genes, associated with cell migration and metastasis." (PMID 39685635, 2024). "C3a and C5a acting through their cognate receptors C3aR, C5aR1 and C5aR2, respectively, are central mediators of tumor promoting responses in the tumor microenvironment." (PMID 35860237, 2022). "Taken together, C5AR2 widely participated in regulating tumor immunity and metabolic signaling pathways." (PMID 34595119, 2021). "Gene set enrichment analysis confirmed that C5AR2 participates in regulating multiple signaling pathways involved in tumorigenesis as well as tumor immunity." (PMID 34595119, 2021). "C5aR1 seems to have pro-tumoral role, whereas C5aR2 has more limited impact but tends to modulate the tumor growth." (PMID 33113844, 2020). "The recognition of the anaphylatoxins by their receptors (C3aR, C5aR1 and C5aR2) present at the surface of some tumor cells leads to the activation of the signaling pathways PI3K, Erk 1/2 and AKT." (PMID 33113844, 2020). "Here, we synthesise advances in intracellular and extracellular complement, with emphasis on complement component 3 (C3) and receptors (C3aR1, C5aR1/CD88, C5aR2/C5L2), highlighting how these pathways shape T-cell metabolism, exhaustion programmes and inflammatory tone within tumours." (PMID 41719156, 2026). "In contrast, C5aR2 expression was localised to the cytoplasm of tumour cells." (PMID 41044172, 2025). "Conversely, C5aR2 plays a more limited yet beneficial role in restraining tumor growth." (PMID 40370471, 2025). "The cGAS-STING pathway is critical for anti-tumour immunity via the recognition of damage-associated molecular patterns (DAMPs), primarily tumour-derived DNA, therefore inhibition of C5aR2 may amplify the host innate immune response to drive tumour clearance." (PMID 38067135, 2023). "Intriguingly, the deficiency of C3aR1, C5aR1, or C5aR2 generated opposite results to the deficiency of C3, with a modest increase in tumor number and growth, whereas the MAC did not play a key role either way." (PMID 32682912, 2021). "C5aR1 and C5aR2 seem to have opposite effects, especially in the tumor context." (PMID 33113844, 2020). "A recent study suggests that C3b could impact tumorigenesis during chronic skin inflammation, in cutaneous squamous cell carcinoma (cSCC) model, but independently of C3aR or the terminal pathway (C5a/C5aR1/C5aR2 and MAC generation), likely by influencing tumor associated macrophages." (PMID 33113844, 2020). "Univariate independent prognostic analysis showed that age (p < 0.001), tumor grade (p < 0.001), PCDH18 (p < 0.05), PPL (p < 0.01), DEPP1 (p < 0.01), VASN (p < 0.001), KCNE4 (p < 0.001), MYBPH (p < 0.001), C5AR2 (p < 0.01), and MARCH4 (p < 0.01) gene expression levels were significantly different." (PMID 39281062, 2022).
tumor (continued). "Specifically, C5aR1 expression was markedly elevated in the tumor tissue derived from patient TS15-88, whereas C5aR2 levels showed no significant variation." (PMID 41353504, 2025).
cancer (50 papers, 2016 to 2025). A tumor composed of atypical neoplastic, often pleomorphic cells that invade other tissues. "Interestingly, deficiency of C3aR1, C5aR1, or C5aR2 produced effects opposite to those observed with C3 deficiency, underscoring the complexity of complement receptor signaling in cancer." (PMID 41300283, 2025). "C5a, C5aR1 and C5aR2 were assessed in cancer cell cytoplasmic (c-) and stromal (s-) expressions in resected PDAC tissues." (PMID 41044172, 2025). "In this present study, expression levels of C5AR2 in different cancer types and normal samples were evaluated using the TCGA and GTEx databases, indicating that in pan-cancer, there were distinct differences of C5AR2 expression across cancerous and normal tissues." (PMID 34595119, 2021). "Analyze of C5AR2 in cancer is scarce and mostly focused on knockout mice models." (PMID 34595119, 2021). "C5AR2 overexpression also upregulated the expression levels of MMP2 and MMP9, which were reported as oncogenes correlated with metastasis and invasion in various cancers." (PMID 34595119, 2021). "To figure out correlations of C5AR2 expression with cancer, we then evaluated and compared C5AR2 expression levels between different cancers and matched noncancerous samples." (PMID 34595119, 2021). "In general, C5AR2 is differentially expressed in most cancerous and noncancerous tissues, and high expression of C5AR2 is significantly connected with poor prognosis in many cancers." (PMID 35909123, 2022).
infection (6 papers, 2011 to 2023). The state of being infected such as from the introduction of a foreign agent such as serum, vaccine, antigenic substance or organism. "We, therefore, used our CEACAM1-humanized mouse model in combination with deficiencies in C3 (C3−/-), C5 (C5−/-), C3aR1 (C3ar1-/-) C5aR1 (C5ar1−/-) or C5aR2 (C5ar2−/-) to monitor Nme nasal colonization following intranasal infection with 105 CFU." (PMID 31274379, 2019). "While only C5aR1 is involved in bacterial clearance, both C5aR1 and C5aR2 seem to be important for the orchestration of the inflammatory response during infection." (PMID 26512700, 2015). "As we used a murine infection model to investigate the role of C5aR1 and C5aR2 in the host response to S. aureus in this study, we first determined the expression pattern of both anaphylatoxin receptors on murine neutrophils." (PMID 26512700, 2015). "As high serum levels of pro-inflammatory cytokine IL-6 have been shown to contribute to severity of S. aureus infection, we determined the levels of serum IL-6 in wild type, C5aR1−/−, and C5aR2−/− mice at 24 h after intravenous infection with S. aureus." (PMID 26512700, 2015). "At 5 d after the infection, C5aR2 was only significantly upregulated in the liver of infected males compared to the saline group (p = 0.02), while C5aR1 expression in the liver was consistently upregulated in both sexes (p < 0.0001 in males and p = 0.002 in females)." (PMID 32373108, 2020). "To test this hypothesis, we compared the levels of CXCL1 in kidneys homogenates of C5aR1−/− and C5aR2−/− mice with that of wild type mice at 12 h of infection." (PMID 26512700, 2015). "The functional role of C5aR2 in the inflammatory responses is at present highly controversial and may certainly have different roles in different systems and infection models." (PMID 26512700, 2015). "The homology between C5aR1 and C5aR2, and new proposed link to cGAS-STING signalling, provide rationale for further investigations C5aR2 in other infection scenarios." (PMID 38067135, 2023). "However, while we did not observe an effect of C3aR or C5aR2 on mouse neutrophil activation during mouse blood infection, this is apparently the case in human whole blood." (PMID 31274379, 2019).
infectious disease (1 paper, 2021). A disorder directly resulting from the presence and activity of a microbial, viral, or parasitic agent in humans. "For example, the different role of C5aR1 and C5aR2 inhibition in these diseases is poorly understood, and inhibition of C5 activation for prolonged time periods results in increased susceptibility to infectious diseases and other undesired effects." (PMID 33917266, 2021).
C5AR2 also shares sentences with these, for which no sentence is quoted: lung carcinoma (18 papers); breast tumors (4); gastric cancer (4); asthma (3); coronary artery disease (3); metabolic syndrome (3); colitis (2); neurodegenerative disease (2); prostate carcinoma (2); retinitis pigmentosa (2); type 2 diabetes (2); vasculopathy (2); acute respiratory distress syndrome (1); acute tubular necrosis (1); airway hyperresponsiveness (1); Allergy (1); autoinflammatory syndrome (1); bacterial infection (1); bladder cancer (1); bladder tumors (1); breast adenocarcinoma (1); chronic obstructive pulmonary disease (1); colorectal cancer (1); endotoxemia (1); familial Mediterranean fever (1); glomerulopathy (1); gout (1); hidradenitis suppurativa (1); inflammation (1); influenza (1).
A further 16 diseases each share a sentence with C5AR2 in 1 paper.